KDR (kinase insert domain receptor)
Description:
Tyrosine-protein kinase that acts as a cell-surface receptor for VEGFA, VEGFC and VEGFD. Plays an essential role in the regulation of angiogenesis, vascular development, vascular permeability, and embryonic hematopoiesis. Promotes proliferation, survival, migration and differentiation of endothelial cells. Promotes reorganization of the actin cytoskeleton. Isoforms lacking a transmembrane domain, such as isoform 2 and isoform 3, may function as decoy receptors for VEGFA, VEGFC and/or VEGFD. Isoform 2 plays an important role as negative regulator of VEGFA- and VEGFC-mediated lymphangiogenesis by limiting the amount of free VEGFA and/or VEGFC and preventing their binding to FLT4. Modulates FLT1 and FLT4 signaling by forming heterodimers. Binding of vascular growth factors to isoform 1 leads to the activation of several signaling cascades. Activation of PLCG1 leads to the production of the cellular signaling molecules diacylglycerol and inositol 1,4,5-trisphosphate and the activation of protein kinase C. Mediates activation of MAPK1/ERK2, MAPK3/ERK1 and the MAP kinase signaling pathway, as well as of the AKT1 signaling pathway. Mediates phosphorylation of PIK3R1, the regulatory subunit of phosphatidylinositol 3-kinase, reorganization of the actin cytoskeleton and activation of PTK2/FAK1. Required for VEGFA-mediated induction of NOS2 and NOS3, leading to the production of the signaling molecule nitric oxide (NO) by endothelial cells. Phosphorylates PLCG1. Promotes phosphorylation of FYN, NCK1, NOS3, PIK3R1, PTK2/FAK1 and SRC.
Synonyms: CD309; FLK1; VEGFR2; VEGFR
Tractability: Small molecule: an approved drug acts on it; a structure with a bound ligand is known; a high-quality ligand is known; it has a high-quality binding pocket; it belongs to a druggable protein family. Antibody: an approved drug acts on it; UniProt places it where antibodies can reach, with high confidence; its Gene Ontology location is reachable by antibodies, with high confidence; UniProt predicts a signal peptide or a membrane-spanning region. PROTAC: UniProt records ubiquitination sites on it; ubiquitination databases record sites on it; a small molecule that binds it is known. Other modalities: a drug acting on it is in phase 2 or 3 trials.
Target class: Tyrosine protein kinase VEGFR family; Enzyme; TK protein kinase group; Protein Kinase; Kinase
Chemical probes: BRIVANIB, CABOZANTINIB (high quality), CHEMBL347537, GOLVATINIB, GW770220A, GW771127A, GW806742X, HG-7-85-01 (high quality), PD005335, PD005394, PD080730, PD080827, PD081161, PD081317, PD081331, PD081337, PD081347, PD081351, PD081476, PD081580, and 62 more
Safety:
Unwanted effects reported when the protein is acted on. In parentheses: how it was acted on, where the effect was seen, and who reports it.
aneurysm (inhibition; cardiovascular; source: Brennan et al. (2024))
decreased appetite (inhibition; central nervous system; source: Brennan et al. (2024))
fatigue (inhibition; source: Brennan et al. (2024))
haemorrhage (inhibition; cardiovascular; source: Brennan et al. (2024))
Hypertension (inhibition; cardiovascular; source: Brennan et al. (2024))
Increased, Developmental Defects (inhibition; source: AOP-Wiki)
myocardial hypoperfusion (inhibition; cardiovascular; source: Brennan et al. (2024))
nausea (inhibition; source: Brennan et al. (2024))
proteinuria (inhibition; renal; source: Brennan et al. (2024))
rash (inhibition; skin; source: Brennan et al. (2024))
vomiting (inhibition; gastrointestinal; source: Brennan et al. (2024))
drug toxicity (source: ClinPGx)
heart disease (cardiovascular system; source: Force et al. (2011))
Hypertension and hand-foot skin reactions (source: ClinPGx)
Gene: Protein-coding gene on chromosome 4 (55,078,476 to 55,125,595, reverse strand). Ensembl gene ENSG00000128052.
Subcellular location: Cell junction; Endoplasmic reticulum; Cell membrane; Cell membrane (Isoform 1); Cytoplasm; Nucleus; Cytoplasmic vesicle; Early endosome; Secreted (Isoform 2); Secreted (Isoform 3)
Subcellular location (Human Protein Atlas): Vesicles; Connecting piece; Cytosol; Mid piece; Nuclear membrane; Principal piece
Pathways (Reactome):
Signal Transduction: Neuropilin interactions with VEGF and VEGFR; VEGF binds to VEGFR leading to receptor dimerization; VEGFA-VEGFR2 Pathway; VEGFR2 mediated cell proliferation
Cellular responses to stimuli: High laminar flow shear stress activates signaling by PIEZO1 and PECAM1:CDH5:KDR in endothelial cells
Disease: Signaling by membrane-tethered fusions of PDGFRA or PDGFRB
Extracellular matrix organization: Integrin cell surface interactions
Gene Ontology:
Molecular function: cadherin binding; growth factor binding; identical protein binding; integrin binding; protein binding; protein tyrosine kinase activity; vascular endothelial growth factor binding; vascular endothelial growth factor receptor activity; Hsp90 protein binding; transmembrane receptor protein tyrosine kinase activity; ATP binding; coreceptor activity; cytokine binding; protein kinase activity
Biological process: branching involved in blood vessel morphogenesis; cellular response to hydrogen sulfide; cellular response to vascular endothelial growth factor stimulus; negative regulation of endothelial cell apoptotic process; negative regulation of gene expression; peptidyl-tyrosine phosphorylation; positive regulation of angiogenesis; positive regulation of blood vessel endothelial cell migration; positive regulation of cell migration; positive regulation of cell migration involved in sprouting angiogenesis; positive regulation of cell population proliferation; positive regulation of endothelial cell chemotaxis; positive regulation of endothelial cell migration; positive regulation of endothelial cell proliferation; positive regulation of ERK1 and ERK2 cascade; positive regulation of focal adhesion assembly; positive regulation of macroautophagy; positive regulation of MAPK cascade; positive regulation of mitochondrial depolarization; positive regulation of mitochondrial fission; positive regulation of nitric oxide-cGMP mediated signal transduction; positive regulation of phosphatidylinositol 3-kinase/protein kinase B signal transduction; positive regulation of positive chemotaxis; positive regulation of protein phosphorylation; protein autophosphorylation; and 21 more
Cellular component: cytosol; endoplasmic reticulum; endosome; Golgi apparatus; membrane raft; nuclear membrane; plasma membrane; cell junction; early endosome; receptor complex; sorting endosome; anchoring junction; cell periphery; cell surface; cytoplasm; cytoplasmic vesicle; external side of plasma membrane; extracellular region; membrane; nucleus
Genetic constraint (gnomAD): Loss-of-function variants: 33 observed, 134.35 expected, observed/expected ratio (o/e) 0.25, 90% interval 0.19 to 0.33. The upper end of that interval is the gene's LOEUF score, 0.33, which puts it in group 1 of 6, group 1 being the genes least tolerant of losing a copy. Missense variants: 1,291 observed, 1,547.6 expected, observed/expected ratio (o/e) 0.83, 90% interval 0.8 to 0.87. Synonymous variants: 553 observed, 565.01 expected, observed/expected ratio (o/e) 0.98, 90% interval 0.91 to 1.05.
Gene-disease validity (ClinGen):
ClinGen rates the evidence that KDR causes each of these diseases.
pulmonary arterial hypertension (autosomal dominant): Definitive. Pulmonary arterial hypertension (PAH) is a group of diseases characterized by mean pulmonary artery pressure >20 mmHg and elevated pulmonary arterial resistance leading to right heart failure.
Cancer hallmarks: angiogenesis (promotes); cell replicative immortality (promotes); tumour promoting inflammation (promotes); proliferative signalling (promotes); invasion and metastasis (promotes)
Homologues: Orthologues: chimpanzee KDR (99% identical), macaque KDR (99% identical), dog KDR (93% identical), pig KDR (93% identical), guinea pig KDR (89% identical), rabbit KDR (88% identical), rat Kdr (86% identical), mouse Kdr (86% identical), tropical clawed frog kdr (60% identical), zebrafish kdr (49% identical). Paralogues in human: FLT1 (43% identical), FLT4 (42% identical), PDGFRA (23% identical), KIT (21% identical), PDGFRB (21% identical), CSF1R (21% identical), FLT3 (19% identical), FGFR2 (19% identical), FGFR1 (18% identical), FGFR3 (18% identical), FGFR4 (17% identical), ROS1 (15% identical), and 41 more.
Diseases named in the same sentence as KDR in open-access papers:
KDR is named in the same sentence as 688 diseases in open-access papers, as found by Europe PMC text mining. Sharing a sentence is not in itself a finding about the gene and the disease. The quoted sentences say what the papers report.
breast carcinoma (469 papers, 1999 to 2026). "KDR mutations have been implicated in multiple cancers, including colorectal cancer, non-small cell lung carcinoma, breast cancer, and AS." (PMID 40666093, 2025). "The expression of KDR contributes to cancer development through vascularity and is associated with metastasis in colon and breast cancers." (PMID 35999337, 2022). "We report that concomitant low ANLN and high KDR gene expression is associated with favorable breast cancer survival." (PMID 31636652, 2019). "In contrast, some studies have shown that polymorphisms located in the KDR gene are associated with the risk of several human diseases such as chronic myeloid leukemia, breast cancer, glioblastoma, colorectal cancer, cardiovascular disease, or type 2 diabetes." (PMID 31405022, 2019). "On the one hand, it has been reported that Flt-1 overexpression improves survival in breast cancer, whereas KDR expression is associated with a poor prognosis." (PMID 15841074, 2005). "Recent findings have shown that the role of ANLN is significant in the immune reaction via association between ANLN and KDR, which may serve as a potential predictor of breast cancer survival." (PMID 35340220, 2022). "Here, we investigate whether KDR expression is associated with members in PI3K/Pten signaling on the prognosis of breast cancer patients." (PMID 31636652, 2019). "Regarding cancer, KDR/VEGFR2 rs2071559 has been identified as a predictive factor in breast cancer, colorectal cancer (CRC), hepatocellular carcinoma (HCC), non-small cell lung cancer (NSCLC), and renal cell carcinoma (RCC)." (PMID 39124599, 2024). "On the time-intensity curve of CEUS, breast cancers with increased peak intensity had about 5 times the frequency of the SNP rs2305948 in KDR compared with those with low peak intensity." (PMID 37120792, 2023). "The vascular endothelial growth factor was found to be a significant regulator of breast cancer angiogenesis, the effects of which were transmitted through the kinase domain receptor (KDR)." (PMID 35057823, 2022). "Several studies have reported that exosome biomarkers (such as CD44, CD47, CXCR4, Del-1, HER2, and KDR) can be used for early diagnosis and prognosis of breast cancer patients." (PMID 32826923, 2020). "The PI3K/Pten pathway is one of the downstream signalings affected by KDR activation and most commonly altered in breast cancer." (PMID 31636652, 2019). "This implicates that ANLN drove the main effect of this interaction and KDR has an amplification effect on ANLN functionalities in breast cancer." (PMID 31636652, 2019). "Conversely, coexpression of SnoN (KdR) antagonized the ability of overexpressed PIAS1 to suppress TGFβ-induced invasive growth of three-dimensional breast cancer cell-derived organoids." (PMID 28493978, 2017). "KDR, being an important protein in chemotaxis, differentiation, and angiogenesis, suggests roles for BC and AA in breast cancers." (PMID 22567014, 2012). "Production of vascular endothelial growth factor (VEGF) and expression of its receptors Flt-1 and KDR was determined in primary cultures of separated epithelial and stromal-enriched cultures derived from ten primary human breast carcinomas." (PMID 10360672, 1999). "In addition, KDR was observed to be upregulated in breast cancer, colorectal cancer, and cell lymphoma." (PMID 38650036, 2024). "Studies using confocal microscopy confirmed that the NPs could precisely target MDA-MB-231 human breast cancer cells overexpressing KDR/Flk-1 protein." (PMID 38247784, 2024).
breast carcinoma (continued). "The differential regulatory relationships between ANLN and KDR in different breast cancer cell lines and normal breast cells suggest a potential network rewiring between more and less malignant states in breast cancer cells, which warrants validation at the transcriptional level." (PMID 31636652, 2019). "Therefore, the increase in peak intensity in breast cancer on CEUS may be related to rs2305948 in KDR and may be a potential indicator of tumor angiogenesis and the response to chemotherapy especially in triple-negative cancer patients." (PMID 37120792, 2023). "All three primary cell surface receptors used for breast cancer subtyping (ER, PR, and HER2) were significantly associated with ANLN and KDR expression, suggesting that the synergistic effect of ANLN and KDR can affect cells’ transition from the triple negative to the luminal-like phenotype." (PMID 31636652, 2019). "Furthermore, down-regulation of KDR expression induces apoptosis in breast cancer cells." (PMID 27911271, 2017). "Consistent with the predictions, synthesized compounds targeting tubulin assembly, KDR, and PDGFRB displayed antiproliferative activity against a panel of cancer cell lines, including breast cancers." (PMID 38424554, 2024). "Ten genes, including CCNB1, CDH1, KDR, RAB25, PRKCA, etc., found which can maintain the high accordance of mRNA–protein for both breast cancer patients and cell lines in basal-like subtypes for the first time." (PMID 36360219, 2022). "Externally modulating breast cancer cells towards low ANLN and high KDR gene expression can transit cells from the triple negative to luminal-like phenotype and sensitize cells to Tamoxifen treatment." (PMID 31636652, 2019). "Following treatment with 11,11’-dideoxyverticillin, the secretion of VEGF from human MDA-MB-468 breast carcinoma cells was lowered, significantly suppressing VEGF-induced tyrosine phosphorylation of the endothelial cell-specific receptors Flt-1 and KDR/Flk-1." (PMID 31569621, 2019). "We aimed to elucidate the drug mechanism and anti-tumor efficacy of TTAC-0001, a novel, fully human anti-VEGFR-2/KDR monoclonal antibody, in mouse orthotopic breast cancer model using multi-modal bioimaging." (PMID 29370209, 2018). "Current data suggests that KDM2A works in conjunction with E2F1 to affect FLT-1 and KDR expression in endothelial cells and MMP expression in breast cancer cells." (PMID 25029110, 2014). "In the present study, we examined VEGF receptor expression and the effect of peptides targeting Flk-1/KDR and NP-1 on apoptosis of 4T1 and MDA-MB-231 breast carcinoma cells." (PMID 15655556, 2005). "Breast cancer epithelial cells and stromal cells produce VEGF and express the VEGF receptors Flt-1 and KDR, indicating that VEGF can play a role not only in angiogenesis but also as an autocrine/paracrine regulator of breast cancer, thereby promoting tumor proliferation and invasion." (PMID 38516703, 2024). "Breast cancer cell lines overexpressing periostin enhance tumor angiogenesis in vivo by activating FAK signaling via integrin-v3 and upregulating the VEGF receptor Flk-1/ KDR in endothelial cells." (PMID 36224629, 2022). "In addition, Src (SRC), VEGFR2 (KDR), IGF1R and PI3Kγ (PIK3CG) have already been successful targets in breast cancer therapy." (PMID 33246450, 2020). "We did not observe any significant alteration on KDR gene expression when modulating that of ANLN in the luminal breast cancer cell line MCF7 and normal breast cell line MCF10A." (PMID 31636652, 2019). "VEGFR-2 phosphorylation was detected above the baseline in case of epithelial breast cancer cells than in endothelial breast cancer cell line, PAEC/KDR, without external VEGF stimulation." (PMID 21556249, 2009).
breast carcinoma (continued). "Initially, expression of Flt-1 and KDR was believed to be restricted to the vascular endothelium, but to date these receptors have also been detected in several types of nonendothelial cells including breast cancer cells, suggesting an autocrine effect of VEGF-A on tumour cells." (PMID 15841074, 2005). "However, an opposite pattern was identified for other of them (VEGFR2/KDR, CYR61/CCN1, IGFBP1, IGFBP4, IGFP6) and no changes for CTGF/CCN2, and IGFP6 across the breast cancer subtypes." (PMID 33531624, 2021).